HIF1A (hypoxia inducible factor 1 subunit alpha)
Diseases named in the same sentence as HIF1A in open-access papers (continued):
Sharing a sentence is not in itself a finding about the gene and the disease.
tumor (continued). "mTOR renders the metabolic program switch to aerobic glycolysis in tumor cells by activating HIF1α, a positive regulator of many glycolytic genes 51,52." (PMID 32626538, 2020). "Our findings suggest that miR-346 augments HIF-1α and inhibits the tumor angiogenic activity in ATV-treated cells." (PMID 32403237, 2020). "HIF1A in turn regulates transcription of NT5E/CD73 whose involvement in tumor development is widely documented as well as those in adaption to hypoxia and promotion of immune-escape." (PMID 32443824, 2020). "In the tumor microenvironment, HIF-1α facilitated the differentiation of M-MDSCs into TAMs, through a mechanism involving CD45 tyrosine phosphatase activity and down-regulation of STAT3 activity." (PMID 33374253, 2020). "Specifically, regulation of vasculature development and angiogenesis together with cell chemotaxis were increased in HIF-1α-KD tumor cells when compared to Mock tumor cells." (PMID 33142239, 2020). "HIF-2α is necessary for the formation of ccRCC xenografts while knockdown of HIF-1α enhances xenograft tumour formation in cell lines that express both HIF-1α and HIF-2α22." (PMID 32807776, 2020). "In the presence of the fragmentation phenomenon, the tumor cells assumed an elongated fibroblast-like form and showed nuclear expression of HIF-1a and Snail." (PMID 32849870, 2020). "The hemoglobin moiety of Gd@HbCe6-PEG delivered oxygen and overcame tumor hypoxia in tumor-bearing mice, as demonstrated by PA imaging and HIF-1α protein expression analysis." (PMID 33052236, 2020). "This antiangiogenic therapy-induced hypoxia within tumor microenvironment increases HIF1α levels (master regulator of hypoxia) resulting in upregulation of various alternative angiogenic factors." (PMID 32002127, 2020). "Since HIF1A is involved in cellular metabolism and in angiogenesis, its decreased expression explains, at least in part, the tumor regression observed in responders." (PMID 32580435, 2020). "This underscores its superior cell-targeting capabilities compared with both pH (low)-insertion peptides and proteins with the cytotoxic TAT-conjugated oxygen-dependent degradation domain of HIF-1α under hypoxic conditions of the tumor microenvironment." (PMID 32002124, 2020). "HIF-1α affects the energy metabolism and proliferation of tumor cells through ubiquitin-proteasome degradation." (PMID 33363466, 2020). "The HIF-1α transcription factor plays a central role in biologic processes under hypoxic conditions including angiogenesis, tumor growth, and epithelial mesenchymal transition in several cancer types." (PMID 32895059, 2020). "In the IF assay, the fluorescence intensity of tumor HIF-1α was decreased more than 50% in mice treated with RT, TNuF, or the combination." (PMID 32872195, 2020). "The transcription of these immunosuppressive molecules is driven by HIF-1α, which is produced due to hypoxia in tumor cells." (PMID 32408623, 2020). "As the tumor starts to grow, oxygen diffusion becomes limited and cancer cells respond to these environmental changes by upregulating HIF-1α." (PMID 32257942, 2020). "According to many evidences, HIF-1a signaling is upregulated in many tumors leading to tumor metastasis, poor patient prognosis and tumor resistance therapy." (PMID 32493394, 2020). "At the tumor margin, blood vessels grow to provide sufficient nutrients and oxygen, allowing for normoxia and routine ubiquitin-mediated degradation of HIF-1α." (PMID 32883954, 2020). "This hydroxylation process allows the HIF-1α recognition by the von Hippel-Lindau (pVHL), a kind of tumor-suppressor protein and the substrate recognition component of an E3 ubiquitin ligase complex that aims HIF-α for proteasomal degradation." (PMID 32587244, 2020). "HIF-1α, as an oxygen-sensitive transcriptional activator, plays a crucial role in tumor survival, progression, and metastasis in hypoxic conditions." (PMID 33457406, 2020).
tumor (continued). "The PI3K/mTOR pathway, activated in NK cells under hypoxia, induces IL-2 expression and upregulates HIF1-α, affecting NK anti-tumor activity." (PMID 32764403, 2020). "Among these genes, it has been reported that EVA1A and HAP1 expression is decreased in tumor tissues, while HIF1α is dramatically increased 36-38." (PMID 32724459, 2020). "Both HIF-1a and VEGF are linked to aggressive tumor types and usually are over-expressed in numerous types of tumors as well as their metastases in human." (PMID 32961987, 2020). "As such, HIF-1α degradation under hypoxic conditions is an essential homeostatic and tumour-suppressing mechanism." (PMID 32093760, 2020). "In intermediate stages of tumor growth, the average relative expression level of Hif1α, VEGFR1 and VEGFR2 were 3.6- (P < 0.01), 2.74- (P < 0.01) and 7.85- fold (P < 0.01), respectively." (PMID 32373503, 2020). "In the absence of cysteine, EglN1, the main prolyl hydroxylase for the HIFα subunit, undergoes oxidative self-inactivation, resulting in HIF1α accumulation and tumor growth." (PMID 31980738, 2020). "Our findings that not only CA IX but also HIF1α level is decreased by propranolol led us to suggest that beta-blockade directly affects the ability of tumour cells to adapt to hypoxic stress." (PMID 33228233, 2020). "HIF-1α expression is able to modulate the recruitment of macrophages to tumor hypoxic areas, leading to strong immune responses." (PMID 33245358, 2020). "Intravenous injection of attenuated Salmonella carrying an HIF-1α siRNA-expressing plasmid in tumor-bearing mice increases the response of PCa cells to cisplatin through promoting the production of reactive oxygen species (ROS)." (PMID 33287240, 2020). "Both glucose transporter-1 (GLUT-1) allowing cellular glucose uptake and MCT4 are induced in the distal hypoxic cells of a tumor, with a clear dependency on HIF-1-α." (PMID 33153193, 2020). "According to Vriend and Reitter, the von-Hippel–Lindau E3 ubiquitin ligase, tumor suppression, plays an important role in the regulation of the ubiquitination process of HIF-1α by binding to its hydroxylation subunit." (PMID 33363343, 2020). "By contrast, the linkage between MCT1 expression and HIF-1α activity is controversial and tumor-dependent." (PMID 33291643, 2020). "For example, histone methyltransferase enhancer of zeste homolog 2 (EZH2) regulates its target gene HIF-1α to influence the status of the tumor microenvironment." (PMID 33109235, 2020). "Immunohistochemical assays were carried out to evaluate tumor hypoxia (HIF-1α, CAIX) and proliferation (Ki67, PCNA) markers." (PMID 32766135, 2020). "We found that there is a significant increase in HIF-1α gene expression in tumor tissues compared to the control tissues." (PMID 32707933, 2020). "The first observations were made almost exclusively on tumor cell lines—it was found that melatonin lowers the level of HIF-1α, e.g., in gliomas, colon cancer cells (HCT116), and pancreatic cancer cells (PANC-1)." (PMID 33519498, 2020). "In the case of tumor nutritional deprivation, fatty acid metabolism regulated by HIF-1α and HIF-2α have gradually shown its importance, but more work, such as epigenetic regulation, still needs to be further studied." (PMID 33109235, 2020). "Our data indicated that TOC significantly increased the TTP for dogs with adenocarcinomas, and decreased the number of intratumoral Foxp3+ Tregs and HIF‐1α+ tumor cells, as well as inhibited VEGFR2 expression." (PMID 32267594, 2020). "On the other hand, the cells of the tumor nucleus exhibit high levels of HIF1α and very low proliferation rates." (PMID 32660072, 2020). "This was confirmed in a recent proof of concept study in 2 different tumor backgrounds (HCT116 and 143B) having a nuclear-encoded NDUFS3 knock-out, where HIF-1α stabilization was abolished, but that tumors were able to re-adapt to the hypoxia response." (PMID 32509579, 2020).
tumor (continued). "Molecular biology studies have shown that in the hypoxic environment, Glut-1, which is one of the downstream target genes of HIF-1α, will be up-regulated accordingly, providing tumor tissue with abundant glucose for cell activity." (PMID 32493238, 2020). "HIF-1α modulates the recruitment of macrophages to hypoxic regions of the tumor and regulates the expression of many genes involved in tumor angiogenesis." (PMID 33081056, 2020). "For example, FBXW7 acts as a tumor suppressor by targeting mTOR, HIF-1α, c-Myc and SREBP1 for degradation." (PMID 33004065, 2020). "A novel lncRNA HIF-1α inhibitor at translation level (HITT) is frequently downregulated in human cancers, resulting in increased angiogenesis and tumor growth via HIF-1α expression." (PMID 33126510, 2020). "In additional experiments in vivo nude mice, the expressions of HIF-1α and miR-301b also increased, and Bim expression decreased, resulting in tumor growth and impairment in programmed cell death." (PMID 33273694, 2020). "One key mechanism downstream of p70S6K1 is activation of PI3K/AKT and MAPK/ERK signaling, which play key roles in inducing tumor cell growth and induction of genes such as hypoxia-inducible factor-1α (HIF-1α)." (PMID 32435616, 2020). "The extracellular lactate coupled with the overexpression of carbonic anhydrase IX and XII (CA-IX and CA-XII) regulated by HIF-1α, promote the acidification of the tumor microenvironment ranging from 6.0 to 6.5." (PMID 32751958, 2020). "Of note, expression of carbonic anhydrase 9, a typical marker of hypoxia, was also reduced in HIF-1α-KD tumor cells." (PMID 33142239, 2020). "The results showed that the mRNA and protein expression levels of CHCHD2 and HIF-1a in tumor tissues were significantly higher than those in the normal tissues." (PMID 32054470, 2020). "The Ki-67 response was significantly lower in tumours with high HIF-1α expression [mean adjusted difference −2.5% (95% CI −0.4, -4.6%) p = 0.018], using an ANCOVA adjusting for baseline HIF-1α, baseline Ki-67, BMI and tumour grade." (PMID 31819173, 2020). "Hypoxia enhances ROS generation via prolongation of the lifetime of the semiquinone radicals; reciprocally, ROS assist tumor cells in adapting to hypoxia via stabilization of HIF1-α." (PMID 33316932, 2020). "Hypoxic conditions are associated with induction of HIF-1α and overexpression of HIF-1α is implicated in initiating angiogenesis, thereby, promoting tumor growth, metastasis and regulation of cellular metabolism to overcome hypoxia." (PMID 32973969, 2020). "We previously identified increased signaling in the ERK1/2 pathway for AAE6 compared to EPE6, suggesting that MSK2 is a key contributing factor to increased hypoxia-inducible factor (HIF)-1α seen in AAE6 over EPE6 cells in the hypoxic tumour environment." (PMID 33121134, 2020). "Hypoxia-inducible factor-1 (HIF-1), ubiquitous in human and mammalian cells, is stable only under hypoxic conditions, and the stabilization of HIF-1α mediates tumor cell invasion and metastasis." (PMID 32934709, 2020). "miR-497 targets multiple genes, including VEGFR2, VEGFA, AEG-1, and HIF-1α to inhibit tumor angiogenesis." (PMID 32993787, 2020). "Nb@IC-NPs improves tumor hypoxia through catalytic reaction and lowers the expression level of HIF-1α." (PMID 33292202, 2020). "Current research shows that HIF-1α promotes mitochondrial clearance in tumour cells mainly by inducing mitochondrial autophagy, also referred as mitophagy." (PMID 32928258, 2020). "The tumor slices were stained with the antibody specific to hypoxia‐inducible factor 1α (HIF‐1α), a protein that has been reported to be upregulated under the hypoxic condition, to track the hypoxia area." (PMID 32995114, 2020). "In this study, we first found that THBS2/TLR4 interaction promotes the tumor growth of CRC by enhanced HIF-1α-mediated glycolysis." (PMID 33244454, 2020).
tumor (continued). "Our results point to a relevant role of the GRK2/HuR/HIF-1α module in the adaptation of malignant cells to tumor microenvironment-related stresses." (PMID 32413989, 2020). "HIF-1α can also promote metastasis, which is a critical step in all malignant cancers in which cancer cells spread away from the primary tumor to distant organs." (PMID 32858793, 2020). "YY1 plays a crucial role in HIF-1α-induced tumor angiogenesis by regulating HIF-1α at post-translational level." (PMID 32226547, 2020). "By means of blocking tumor HIF-1α expression, TNuF can effectively enhance the anticancer response of RT." (PMID 32872195, 2020). "An increase in the expression level of HIF-1α leads to the metabolic reprogramming of tumor cells, enabling them to avoid hypoxic conditions, via invasion and metastasis, and also to improve oxygen availability, via angiogenesis and neovascularization." (PMID 32849870, 2020). "Molecular mechanism responses to hypoxia are predominantly mediated by the hypoxia-inducible factor (HIF)-1α, which transactivates several genes essential for adaptation and is maintains tumor survival." (PMID 32823915, 2020). "Epithelial–mesenchymal transition (EMT) will be induced by activating HIF-1α, and the tumor cells will lose their epithelial phenotypes but acquire mesenchymal phenotypes with migration ability, enhancing the tumor invasiveness and the metastatic potential." (PMID 32974136, 2020). "The nuclear transcription factor, HIF-1α, is a crucial biomarker of the hypoxia tumor microenvironment, which is due to the rapid proliferation of tumor cells." (PMID 32328193, 2020). "The present study revealed that activated HSCs increased HIF-1α expression at the mRNA and protein levels and promoted tumor cell activities." (PMID 32895059, 2020). "HIF-1α plays a dominant role in tumor progression and appears to be an obvious significant prognostic factor in NSCLC." (PMID 32847073, 2020). "E3 ligase MDM2, PARKIN and HUWE1 can catalyze ubiquitination of HIF-1α and targets it for degradation, thus exerting an anti-tumor effect." (PMID 33004065, 2020). "The rapid tumor growth itself induces hypoxia and ROS accumulation, also maintaining HIF1α activity." (PMID 33374292, 2020). "On the other hand, the deletion of HIF1-α inhibits not only tumor growth but the infiltrative capability of NK cells, thus increasing VEGF bioavailability and promoting tumor progression and metastasis." (PMID 32764403, 2020). "GLUT1 and GLUT3 are direct target of HIF-1α, providing a link between hypoxia, Warburg effects, tumor growth and progression." (PMID 33291643, 2020). "In this study, authors have found significant decrease in event free survival and overall survival when immunoexpression of HIF-1α is considered positive for ≥ 10% of tumour cells." (PMID 32722460, 2020). "And through the analysis of cellular immunofluorescence and immunohistochemistry experiments, we found that the IQuCS@Zr-PEG NSPs can downregulate the expression of HIF-1α under MW irradiation, which reflected the reoxygenation of tumor cells from the side." (PMID 32292521, 2020). "The lack of survival difference based on both mRNA and protein expression in this large cohort of ccRCC patients, strongly argue against a tumor suppressive role for HIF1α in ccRCC patients." (PMID 33077781, 2020). "The correlations between [18F]HX4 uptake and HIF1α expression at the cellular level confirm previous preclinical work where [18F]HX4 tumor uptake was correlated to pimonidazole staining." (PMID 33105540, 2020). "In EwS, hypoxia has been found to protect tumor cells against anticancer drugs, while suppression of HIF1α enhanced drug‐induced apoptosis." (PMID 33047515, 2020). "Based on this finding, we examined the correlation between p-STAT3 and HIF-1α protein expression in tumor samples." (PMID 31942180, 2020).
tumor (continued). "The treatment with Cy, in both tumor models, and with Cy+Los in M-406 tumors, decreased significantly the number of HIF1-α positive cells per field compared to Control group (P < 0.05)." (PMID 32850009, 2020). "HIF-1α has a relevant role in oxygen homeostasis, and experimental evidence has indicated that it is a major regulator of normal and tumor cell adaption to hypoxic stress." (PMID 31947661, 2020). "In the case of LMP1, different cargos have been found to be packaged into EVs, including EGF receptor (EGFR), fibroblast growth factor 2 (FGF-2), PI3K, and HIF1α, which play major roles in angiogenesis, tumor growth, and metastasis." (PMID 32546618, 2020). "Hypoxia in tumor tissues inhibits the degradation of hypoxia-inducible factor-1α (HIF-1α) and increases its local accumulation." (PMID 32211041, 2020). "Hypoxic tumor microenvironment induces the expression of VEGF through the transcription factor HIF-1a for the generation of new blood vessels, a process known as angiogenesis." (PMID 32106613, 2020). "Numerous studies have suggested that AKT/mTOR is involved in the Warburg effect by activating HIF-1α or c-Myc in tumor cells." (PMID 32685545, 2020). "The authors discovered that HIF-1α regulates glucose metabolism-related rearrangements in PDAC and that the expression of HIF-1α in tumor tissue is higher than that in surrounding normal tissues even under normoxic conditions." (PMID 33256814, 2020). "This resistance was overcome by co-administration of an HIF-1α inhibitor and chemotherapeutics, preventing tumor relapse in vivo." (PMID 33266219, 2020). "HIF1α is another key regulator of tumor growth and angiogenesis as a transcriptional regulator of VEGFA." (PMID 32070413, 2020). "The HIF-1α pathway plays an important role in tumor progression, but the specific mechanism of HIF-1α promoting tumor cell proliferation is not yet fully understood." (PMID 32211041, 2020). "Hypoxia is a crucial microenvironmental condition for tumor pathophysiology, including tumor metastasis, and HIF-1α is a key molecule that is highly expressed under hypoxia." (PMID 32883954, 2020). "Collectively these analyses demonstrate that Cre activity occurs equivalently for all floxed genes and that Hif1a and Hif2a are deleted in the tumours arising in the relevant mouse backgrounds." (PMID 32807776, 2020). "A previous report showed that high HIF-1α expression correlated to tumor malignancy in liver compared with some metastatic organs such as bone and lung." (PMID 32895059, 2020). "Overexpression of hypoxia-inducible-factor 1α (HIF-1α) strongly influence both tumor proliferation and lymph node metastasis in ESCC." (PMID 33604284, 2020). "It is considered a mitochondria-localized tumor suppressor, which opposes reprogramming of cancer cell metabolism through HIF1α destabilization." (PMID 32961898, 2020). "Using an autochthonous mouse model of ccRCC with Vhl deletion, here the authors show that HIF-1α is necessary for tumor formation, while HIF-2α deletion has only a moderate effect." (PMID 32807776, 2020). "Taken together, our results suggest that compound 9 exerts an antiangiogenic activity via the dual downregulation of VEGF/VEGFR2-mediated signaling in ECs and HIF-1α/VEGF expression in tumor cells." (PMID 32751120, 2020). "Recent researches showed MT2-MMP was a new component in an anti-apoptotic pathway network in tumor cells and was also a novel target of HIF-1α." (PMID 32587480, 2020). "Further research and discovery regarding HIF-1α regulation by oxidative stress is warranted for better understanding of disease development and potential therapeutics for pathologies in tumor." (PMID 32719331, 2020). "In the previous experiment, we found that HIF-1α was also upregulated in tumor tissues synchronized with HMGB1." (PMID 32328193, 2020). "Rapid tumor cell proliferation creates hypoxia or oxygen deficit and stabilizes HIF1α, the main VEGF regulator along with growth factors and oncogenes." (PMID 32211322, 2020).